OMA1 (OMA1 zinc metallopeptidase)
Diseases named in the same sentence as OMA1 in open-access papers (continued):
Sharing a sentence is not in itself a finding about the gene and the disease.
gynecologic cancer (2 papers, 2019 to 2022).
Mitochondrial myopathy (2 papers, 2022 to 2024). "This OMA1-mediated protective response was shown to be essential for the survival of mice in a knock-in model of mitochondrial myopathy in which an abnormal protein accumulated the inner membrane." (PMID 39570915, 2024).
sarcoma (2 papers, 2023 to 2025). A usually aggressive malignant neoplasm of the soft tissue or bone. "Using prime editing, we developed a mouse sarcoma cell line in which OMA1 cysteine 403 was mutated in alanine." (PMID 37024121, 2023). "We confirmed in murine sarcoma cells that the mutation of cysteine 403 abrogated OMA1 proteolytic activity toward the OPA1 protein and also possibly its autocatalytic activity." (PMID 37024121, 2023). "We therefore probed the involvement of the OMA1/OPA1 pathway in a mouse sarcoma model and tested whether the level of OMA1 and OPA1 expressions was associated with clinical outcome and immune variables in human soft tissue sarcomas (STS)." (PMID 37024121, 2023). "Our results in sarcoma suggest that the expression level of OMA1 and OPA1 varies significantly among sarcoma subtypes with complex genomics." (PMID 37024121, 2023). "The relevance of our findings in a mouse sarcoma model was questioned by exploring the levels of expression of the transcripts coding for OMA1 and OPA1 in a large series of STS with complex genomics, documented in various databases." (PMID 37024121, 2023).
atherosclerosis (1 paper, 2024). A disease characterized by the build-up of fatty material and calcium deposition in the arterial wall resulting in partial or complete occlusion of the arterial lumen. "We found several novel activation pathways between d-flow and atherosclerosis, such as Zn2+-dependent inner mitochondrial membrane metalloendopeptidase OMA1, SR 1078 (a selective agonist of RORα and RORγ) and EIF2AK3 (eukaryotic translation initiation factor 2 alpha kinase 3)." (PMID 38646649, 2024).
bone tumors (1 paper, 2024). "The role of OMA1 in human osteosarcoma (OS), one of the most prevalent malignant bone tumors, remains elusive." (PMID 39487118, 2024).
breast adenocarcinoma (1 paper, 2019). "However, whether OMA1 plays a role in the development and progression of breast adenocarcinoma is unknown." (PMID 31611601, 2019).
breast tumors (1 paper, 2019). "We anticipate that the reduced OMA1 expression-associated consequences need not be restricted to breast tumors and may possibly be recapitulated in other cancer settings as well." (PMID 31611601, 2019).
cataract (1 paper, 2019). Partial or complete opacity of the crystalline lens of one or both eyes that decreases visual acuity and eventually results in blindness. "Despite the accumulation of L‐OPA1, YME1L‐deficient mice developed microphthalmia and cataracts independent of the presence of OMA1." (PMID 30389680, 2019).
clear cell carcinoma of the kidneys (1 paper, 2024). "For example, the level of OMA1 in some tumors, such as renal pheochromocytoma, clear cell carcinoma of the kidneys, pheochromocytoma, and paraganglioma, is lower than in normal tissues." (PMID 39487118, 2024).
cognitive disorders (1 paper, 2022). A disease affects cognitive processes. "Increasing evidence has shown that CHCHD2 and CHCHD10 are associated with cognitive disorders and motor neuron diseases through their interactions with proteins such as OMA-1, OPA-1, TDP43, PINK, and p62." (PMID 36061599, 2022). "The review highlights the different roles played by CHCHD2 and/or CHCHD10 binding to various target proteins (such as OPA-1, OMA-1, PINK, and TDP43) and reveals their non-negligible effects in cognitive impairments and motor neuron diseases." (PMID 36061599, 2022).
glomerular disease (1 paper, 2026). "Our data underscore the potential of OMA1 inhibition as a therapeutic strategy for glomerular diseases and warrant further investigation." (PMID 41509918, 2026). "While our study establishes the role of OMA1 in mitigating glomerular disease in PHB2-deficiency, we did not directly assess OPA1 cleavage in podocytes." (PMID 41509918, 2026). "Additionally, our findings suggest a positive effect of Oma1 ablation on mTORC1 signaling, which may contribute to understanding why pharmacological inhibition led to the alleviation of glomerular disease in various rodent models." (PMID 41509918, 2026). "As OMA1 is known to cleave multiple substrates, including DELE1, future studies will be necessary to determine the relative contributions of these pathways in podocyte biology and glomerular disease." (PMID 41509918, 2026).
HCMV infection (1 paper, 2023). "The expression levels of mitochondrial fusion-related proteins including MFN1, OPA1, and OMA1 were increased in HCMV-infected THP-1 cells, as well as mitochondrial fusion after HCMV infection." (PMID 36939338, 2023). "Meanwhile, HCMV infection upregulated the expression levels of MFN1 and OPA1 and overlapped with the M-AAA protease 1 homolog (OMA1)." (PMID 36939338, 2023).
hypothyroidism (1 paper, 2024). Abnormally low levels of thyroid hormone. "As OPA1 and OMA1 are critical for the maintenance of mitochondrial integrity and function, their decline suggests an impaired mitochondrial fusion process in hypothyroidism, likely leading to mitochondrial dysfunction and impaired cellular energy production." (PMID 39301315, 2024). "On the other hand, the livers of hypothyroid rats treated with either 3,5-T2 or T3 exhibit increased mitochondrial fusion, as evidenced by increased OPA1 and OMA1 levels, possibly counteracting the deleterious effects of hypothyroidism on mitochondrial dynamics." (PMID 39301315, 2024). "Data obtained in the present study show that hypothyroidism significantly alters mitochondrial dynamics, leading to a decrease in OPA and OMA1 levels in the liver." (PMID 39301315, 2024).
kidney injury (1 paper, 2026). Trauma to the kidney. "In a mouse model of ischemic kidney injury, mitochondrial fragmentation due to OPA1 proteolysis by OMA1 has been implicated as a contributing factor to renal tubular injury and could be rescued by OMA1 ablation." (PMID 41509918, 2026).
lymphoma (1 paper, 2025). A malignant (clonal) proliferation of B- lymphocytes or T- lymphocytes which involves the lymph nodes, bone marrow and/or extranodal sites. "OMA1 activation causes excessive proteolytic cleavage of OPA1 and increased integrated stress response (ISR)-induced apoptosis in lymphoma cells." (PMID 41146909, 2025). "More specifically, BTM pyrazolo-thiazoles (BTM-3528 and BTM-3566) selectively kill lymphoma cells by allosterically turning on OMA1, which then cleaves its two key substrates, OPA1 and DELE1, to couple mitochondrial dynamics to the ISR and intrinsic apoptosis." (PMID 41146909, 2025). "In lymphoma cell lines like BJAB and HCT-116, BTM compounds cause OMA1-dependent loss of long OPA1, inducing fission, without the immediate mitochondrial depolarization or acute respiration impairment." (PMID 41146909, 2025).
myocardial infarct (1 paper, 2020). "As detailed in Section 5 and Section 8, pharmacologic inhibition of DRP1 and OMA1, as well as upregulation of autophagy, have been shown in an as-yet limited number of studies to evoke cardioprotection and reduce myocardial infarct size." (PMID 31952189, 2020).
nephropathies (1 paper, 2026). "Our findings suggest that targeting OMA1 may offer a therapeutic benefit in a broader spectrum of nephropathies characterized by mitochondrial distress, irrespective of the initiating insult." (PMID 41509918, 2026).
Parkinson's (1 paper, 2018). "Nevertheless, understanding how L‐OPA1 processing varies in syndromic OPA1 and common diseases of dopaminergic cell loss such as Parkinson's and promoting L‐OPA1 stability (eg, by OMA1 inhibition) could pave the way for novel targeted therapies against mitochondrial dysfunction in neurodegeneration." (PMID 29604226, 2018).
soft tissue sarcoma (1 paper, 2023). A malignant neoplasm arising from muscle tissue, adipose tissue, blood vessels, fibrous tissue, or other supportive tissues excluding the bones. "Patients with complex genomic soft tissue sarcoma showed variations in the level of OMA1 and OPA1 transcripts." (PMID 37024121, 2023).
testicular cancer (1 paper, 2019). A primary or metastatic malignant neoplasm that affects the testis. "Intriguingly, results of the Human Protein Atlas Consortium initiative report low OMA1 protein levels in breast and testicular cancer tissues, as well as in lymphomas." (PMID 31611601, 2019). "Moreover, OMA1 protein levels were reported to be extremely low in breast and testicular cancer tissues, as well as lymphomas." (PMID 31611601, 2019).
tumor (7 papers, 2019 to 2025). "OMA1 deficiency significantly reduced OS tumor weight and size." (PMID 39487118, 2024). "Therefore, consistent with findings in tumor samples, OMA1 deficiency enhances apoptosis in OS cells." (PMID 39487118, 2024). "In mitochondrial extracts, only L- and S-OMA1 were detected, with a predominance of the S-OMA1 isoform that may witness the presence of an endogenous mitochondrial stress associated with OMA1 autocatalysis in this tumor cell line." (PMID 37024121, 2023). "Knockout of OMA1 in OS cells significantly reduces OS tumor weight and size, and lung metastatic nodules in BALB/c nude mice." (PMID 39487118, 2024). "Here, we observed increased OMA1 expression in OS tumor tissues collected from four patients with advanced OS." (PMID 39487118, 2024). "Immunohistochemistry (IHC) analysis showed a marked elevated OMA1 level in tumor tissues (T) compared with para-carcinoma tissues (P) from the same patient." (PMID 39487118, 2024). "Immunohistochemistry analysis showed a significant decrease in Ki67 and an increase in Cleaved-caspase 3 in OMA1 knockout tumor samples." (PMID 39487118, 2024). "Consistent results were observed in Western blotting analysis; the protein level of OMA1 was markedly increased in tumor samples." (PMID 39487118, 2024). "As GSK3β synergizes with its downstream β-catenin to regulate tumor cell proliferation, we investigated the effect of OMA1 depletion and overexpression on GSK3β and β-catenin expression in OS cells." (PMID 39487118, 2024). "We performed a Western blot analysis on protein extracts from enriched CD45-negative tumor cells to monitor the expression of OMA1, OPA1, and DELE1 isoforms involved in the handling of mitochondrial and ER stress, respectively." (PMID 37024121, 2023). "Recently, the mitochondrial protease OMA1, which regulates internal and external signals in mitochondria by cleaving mitochondrial proteins, was shown to be related to tumor progression." (PMID 35163244, 2022). "Here, we observed elevated OMA1 expression in OS tumor tissues from four patients with advanced OS." (PMID 39487118, 2024). "This suggested that in mutant tumor cells, C403A OMA1 or other proteases might be able to cleave DELE1 under basal conditions." (PMID 37024121, 2023). "Based on our results, one could propose to design modulators of OMA1 or OPA1 activation targeting the redox switch or the fusiogenic function of OPA1 to enhance tumor cell fragility and immunostimulation." (PMID 37024121, 2023). "OMA1 may promote tumor development by driving metabolic reprogramming and increasing oxidative stress." (PMID 35163244, 2022). "Moreover, consistent with the observed filapodia structures, post-quiescent oma1−/− MEFs displayed abnormal actin distribution patterns resembling rearrangements reported in neoplasms." (PMID 31611601, 2019). "CPX also reduces tumor development of control OS cells but not OMA1-deficient OS cells in mice." (PMID 39487118, 2024). "Given that mitochondrial stress-sensitive peptidase OMA1 controls mitochondrial dynamic balance to maintain bioenergetic homeostasis and mitochondrial dysfunction contributes to tumorigenesis, we evaluated OMA1 expression in four OS tumor tissues collected from patients with advanced OS." (PMID 39487118, 2024). "Thus, OMA1 inactivation increased the development of anti-tumor immunity." (PMID 37024121, 2023). "We next investigated whether depletion of OMA1 promotes EMT in tumor cells." (PMID 31611601, 2019). "This type of signature evokes that found in the OMA1 mutant model that was developed in which stress-induced OPA1 cleavage is prevented, limiting adaptation to mitochondrial stress of tumor cells and exposing to increased immunogenic cell death." (PMID 37024121, 2023).
tumor (continued). "Similar correlation analysis was conducted for mRNA expression datasets for OMA1 and mesenchymal marker genes such as TWIST1, ZEB1, and Fibronectin (FN1) using the input, TCGA_Tumor (BRCA Tumor) and TCGA_Normal (BRCA_Normal) with Pearson’s statistical test." (PMID 31611601, 2019). "IHC analysis showed that OMA1 was essentially undetectable, and Ki67 decreased markedly in OMA1 knockout tumor samples, indicating that lack of OMA1 reduces OS cell proliferation and tumorigenesis in vivo." (PMID 39487118, 2024).
cancer (6 papers, 2019 to 2026). A tumor composed of atypical neoplastic, often pleomorphic cells that invade other tissues. "Consistently, reduced OMA1 expression is linked to better outcomes in patients with certain cancers, such as squamous cell carcinoma." (PMID 39487118, 2024). "Depending on the type of cancer, a decrease in OMA1 expression has been linked to a varying prognosis for patients." (PMID 39487118, 2024). "Whereas the level of expression of these proteins is relatively independent from their activation status, few contradictory studies reported an association of OMA1 levels with susceptibility to cancer." (PMID 37024121, 2023). "In this study, we demonstrate that cancer cells that enter this resistant cell state in response to cisplatin increase OMA1 activity and decrease mitochondrial fusion and function to combat oxidative stress." (PMID 41256627, 2025). "In summary, our findings suggest that cancer cells surviving chemotherapy increase OMA1 activity in response to oxidative stress." (PMID 41256627, 2025). "Although there are currently no specific OMA1 inhibitors developed, this work contributes to the need for the screening of compounds against OMA1 activity, as other groups have solely used genetic mechanisms to inhibit OMA1 in various cancer models." (PMID 41256627, 2025). "Further work involves knocking out OMA1 in PC3 cells to assess its role in the entrance to this cancer cell state." (PMID 41256627, 2025). "We reasoned that by interrupting OMA1 function in cancer cells, one might interfere with the induction of stress response pathways and enhance cancer cell death." (PMID 37024121, 2023). "Testing OMA1 protein levels in cancer patients may therefore serve as a robust predictive marker for treatment responses and prognosis in development of personalized treatment strategies." (PMID 31611601, 2019). "We thus hypothesized that OMA1 function may be attenuated in these cancers and such a setting could be an important contributor to malignancy." (PMID 31611601, 2019). "Given that glycolysis, rather than OXPHOS, produces large amounts of ATP in cancer cells, aberrant expression of OMA1 in various types of cancer has been reported in The Cancer Genome Atlas (TCGA) database." (PMID 39487118, 2024).
neurodegenerative disease (3 papers, 2022 to 2025). A disorder of the central nervous system characterized by gradual and progressive loss of neural tissue and neurologic function. "Furthermore, in rodent studies, mice with neuron‐specific PHB2 deficiency exhibited neurodegenerative disease with a reduced lifespan that could be rescued by additional ablation of Oma1." (PMID 41388823, 2025). "Thus, OMA1 and the ISR are potential therapeutic targets for the prevention and treatment of neurodegenerative diseases." (PMID 36290724, 2022).
cardiovascular disease (2 papers, 2018). "Thus, leptin targeting the GSK3/OMA1/OPA1 signaling pathway can optimize hMSCs therapy for cardiovascular diseases such as MI." (PMID 29748581, 2018).
infection (2 papers, 2022 to 2025). The state of being infected such as from the introduction of a foreign agent such as serum, vaccine, antigenic substance or organism. "As with HRI KO cells, OMA1 KO cells were deficient for the activation of ATF4 during infection." (PMID 40811546, 2025).
OMA1 also shares sentences with these, for which no sentence is quoted: myopathy (2 papers); amyotrophic lateral sclerosis (1); breast ductal carcinoma (1); Cerebral ischemia (1); endocervical adenocarcinoma (1); esophageal carcinoma (1); gastric cancer (1); glaucoma (1); glomerulosclerosis (1); heart disease (1); Hepatic steatosis (1); ischemic cardiomyopathy (1); ischemic stroke (1); leiomyosarcoma (1); liposarcoma (1); metabolic disorders (1); microphthalmia (1); motor neuron diseases (1); myxofibrosarcoma (1); nephrotic syndrome (1); optic atrophy (1); osteosarcoma (1); paraganglioma (1); pheochromocytoma (1); squamous cell carcinoma of the cervix (1); type 2 diabetes mellitus (1); undifferentiated pleomorphic sarcoma (1).